IL12A (interleukin 12A)
Diseases named in the same sentence as IL12A in open-access papers (continued):
Sharing a sentence is not in itself a finding about the gene and the disease.
central obesity (1 paper, 2017). "In healthy controls, the EBI3 rs4905 and EBI3 rs4740 were associated with low risk of central obesity and increased risk of high levels of AST, whereas the IL-12A rs583911 correlated with high risk of increased SAT and IL-12A rs568408 with diminished risk of metabolic syndrome." (PMID 28321150, 2017).
Chronic colitis (1 paper, 2024). A chronic inflammatory disease of the large intestine (colon, cecum and rectum). "The reduction of Il12a, Il12b, and Il23a expression was also observed in chronic colitis." (PMID 39113810, 2024).
chronic gastritis (1 paper, 2016). Inflammation of the stomach that is chronic in nature. "H. pylori infection results in increased expression of TNFA, IL6, IL12A and IL2 in the gastric mucosa, in addition to the effect of chronic gastritis, and for TNF‐α and IL‐2 proteins, this increase was mainly observed in inflammatory cells." (PMID 26945693, 2016). "Herein, we assessed whether H. pylori infection and its eradication, beyond its cagA virulence genotype, change the expression of inflammatory mediators (TNFA, IL6, IL1B, IL12A, IL2 and TGFBRII) in chronic gastritis patients." (PMID 26945693, 2016). "mRNA and protein expression of TNFA, IL6, IL1B, IL12A, IL2 and TGFBRII and miRNAs miR‐103a‐3p, miR‐181c‐5p, miR‐370‐3p, miR‐375 and miR‐223‐3p were evaluated in tissue samples from 20 patients with chronic gastritis H. pylori negative (Hp−) and 31 H." (PMID 26945693, 2016).
dengue disease (1 paper, 2008). Dengue fever (DF), caused by dengue virus, is an arboviral disease characterized by an initial non-specific febrile illness that can sometimes progress to more severe forms manifesting capillary leakage and hemorrhage (dengue hemorrhagic fever, or DHF) and shock (dengue shock syndrome, or DSS). "First, the profile showed characteristics of a general antiviral response with up-regulation of IFNG, which is an established major antiviral cytokine in dengue disease, together with up-regulation of IL12A, a potent stimulator of IFN-γ production." (PMID 18398488, 2008).
dyslipidaemia (1 paper, 2018). "Gene-gene interaction was shown between ENHO rs2281997 and IL18 rs360719 with respect to dyslipidaemia by K/DOQI and IL12A rs568408 with respect to atherogenic dyslipidaemia." (PMID 30413149, 2018). "Therefore, we analysed gene-gene epistatic interactions between ENHO SNPs (rs2281997, rs72735260) and Th1 cell cytokine gene SNPs (IL12A rs568408, IL12B rs3212227, and IL18 rs360719) with respect to both types of dyslipidaemia." (PMID 30413149, 2018).
eosinophilia (1 paper, 2023). "We found that the transcript levels of Il12a, Il12b, and Il23a were increased in the lungs of neutrophilia-dominant mice compared to the eosinophilia-dominant mice or the control mice." (PMID 37898756, 2023).
food allergy (1 paper, 2024). Gastrointestinal disturbances, skin eruptions, or shock due to allergic reactions to allergens in food. "However, induction of a food allergy to OVA led to significant upregulation of Il17a along with elevated expression of Il1b and Il12a, indicating that allergic inflammation augments the inflammatory response to C. albicans in the glandular stomach." (PMID 39347572, 2024).
gingivitis (1 paper, 2019). A disorder involving inflammation of the gums; may affect surrounding and supporting structures of the teeth. "Notably, MAP2K4 from the MAPK pathway was down-regulated (>2-fold) specifically by the commensal biofilm, and the immune stimulatory molecule IL12A was down-regulated >10-fold by the cariogenic biofilm (compared to 2-fold down-regulation by commensal biofilm and no regulation by gingivitis biofilm)." (PMID 31448244, 2019).
graft versus host disease (1 paper, 2022). An immune system disorder that occurs after allogeneic hematopoietic stem cell transplant and is a reaction of donor immune cells against host tissues. "Transcripts for the pro-inflammatory cytokine Il12A, a mediator of graft versus host disease, Il18 and its receptor, Il21r, and Il1rl1 were lower in NP over FAT cells." (PMID 36406265, 2022).
gram-negative bacterial infections (1 paper, 2025). Infections caused by bacteria that show up as pink (negative) when treated by the gram-staining method. "When the infected cell line was treated with N and αT, IL-12A expression was significantly higher than in the control, especially in response to Gram-negative bacterial infections (78 pg/ml and 123 pg/ml, respectively)." (PMID 40873569, 2025).
gram-positive bacterial infections (1 paper, 2025). Infections caused by bacteria that retain the crystal violet stain (positive) when treated by the gram-staining method. "IL-12A levels were moderately induced across both Gram-negative and Gram-positive bacterial infections, though it remained at low levels and became undetectable by 48 h." (PMID 40873569, 2025). "In the control condition, both Gram-negative and Gram-positive bacterial infections induced a moderate level of IL-12A expression, with undetectable concentrations after 48 h." (PMID 40873569, 2025).
Granuloma (1 paper, 2021). A compact, organized collection of mature mononuclear phagocytes, which may be but is not necessarily accompanied by accessory features such as necrosis. "While IL-12A was significantly upregulated in cysts (P < 0.01), IL-17A represents the highest significantly upregulated gene in granulomas (P < 0.0001)." (PMID 34539639, 2021).
head and neck cancer (1 paper, 2023). A primary or metastatic malignant neoplasm affecting the head and neck. "Numerous CD-related genes have been found to be altered in head and neck cancers, such as LPP (lipoma-preferred partner), SCHIP1 (schwannomin-interacting protein 1), and IL12A (interleukin-12 subunit alpha)." (PMID 36833303, 2023).
Hepatic steatosis (1 paper, 2014). Steatosis is a term used to denote lipid accumulation within hepatocytes. "Accordingly, in the present study we have shown that both increased levels of Il12a, Il12b, Il18, Ifng, Tnfa, and Il10 mRNA expression seen in the liver of HFH fed mice and hepatic steatosis were reduced in HFL fed mice." (PMID 25251155, 2014).
hepatitis B (1 paper, 2013). "In HD patients, the studied IL-12 polymorphic variants seem to be associated with the anti-HBs phenotype (a) with borderline significance for IL-12A in hepatitis B vaccinated patients, and (b) significantly for IL-12B in patients who underwent natural HBV infection." (PMID 24158609, 2013).
Hyperglycemia (1 paper, 2016). An increased concentration of glucose in the blood. "Also, while our in vitro data explored the inhibition of IL‐6 during of acute hyperglycemia, our in vivo RNA‐seq data from the glucose‐octreotide protocol suggest that multiple other immune transcripts increase with hyperglycemia including IL‐12A, which is important in TH1 development." (PMID 27042306, 2016).
intracranial aneurysms (1 paper, 2016). "Authors of a case-control study suggested that the IL-12A and IL-12B independently and jointly was involved in the susceptibility to intracranial aneurysms in a Chinese population." (PMID 26830841, 2016).
leprosy (1 paper, 2008). Leprosy is a chronic infectious disease affecting primarily the skin and peripheral nervous system. "IL12RB2 has been associated with leprosy but not TB and, to our knowledge, IL12A has not been associated with TB in any study." (PMID 19116662, 2008).
lung adenocarcinoma (1 paper, 2021). A carcinoma that arises from the lung and is characterized by the presence of malignant glandular epithelial cells. "The expression levels of IL12A and KIR3DL2 in lung adenocarcinoma, and KIR3DL2 in lung squamous cell carcinoma were significantly lower than in adjacent normal tissues and decreased as the clinical stage increased." (PMID 34943992, 2021).
lymphoma (1 paper, 2023). A malignant (clonal) proliferation of B- lymphocytes or T- lymphocytes which involves the lymph nodes, bone marrow and/or extranodal sites. "The results of statistical analysis in our research found that rs2069718 of IFNG and rs6887695 of IL12A were significantly associated with OS in lymphoma patients." (PMID 37329186, 2023). "In addition, the rs6887695 of IL12A was also significantly associated with the survival of lymphoma under the dominant, overdominant or codominant models." (PMID 37329186, 2023). "More importantly, the IFNG (rs2069718) and IL12A (rs6887695) were associated with the overall survival (OS) of lymphoma patients remarkably, and the adverse effects of GC genotypes could not be offset by Bonferroni correction for multiple comparison in rs6887695 especially." (PMID 37329186, 2023). "LASSO regression and univariate Cox regression indicated that the rs2069718 of IFNG and rs6887695 of IL12A were correlated with the survival of the lymphoma patients under dominant and codominant models (all p < 0.05), and the AUC (Area Under Curve) were all greater than 0.62." (PMID 37329186, 2023). "Therefore, we identified that the SNPs associated with lymphoma patients' survival were the rs2069718 of IFNG and the rs6887695 of IL12A." (PMID 37329186, 2023). "Therefore, in order to further determine the role of the two genetic polymorphisms on the progression and prognosis of lymphoma, we explored the association of the two genetic polymorphisms and the mRNA expression levels of IFNG and IL12A in some available lymphoma samples." (PMID 37329186, 2023).
metabolic syndrome (1 paper, 2017). A cluster of metabolic risk factors for CARDIOVASCULAR DISEASES and TYPE 2 DIABETES MELLITUS. "These polymorphisms were also associated with decreased risk of T2DM (EBI3 rs428253) and metabolic syndrome (IL-12A rs2243115) in premature CAD patients." (PMID 28321150, 2017). "In addition, we found that the IL-12A rs568408 correlated with decreased risk of metabolic syndrome (Padd = 0.042) and the IL-12A rs583911 was associated with high levels of SAT (Phet = 0.004, Pcod1 = 0.017)." (PMID 28321150, 2017).
neuroendocrine carcinoma (1 paper, 2020). A malignant neuroendocrine neoplasm composed of cells containing secretory granules that stain positive for NSE and chromogranin. "Ter-Minassian and colleagues reported an association of IL12A with neuroendocrine cancer." (PMID 32973967, 2020).
pancreatic cancer (1 paper, 2024). "Finally, our analysis of inflammatory biomarkers shows that AIF-1, IL-12A and IL-18 are directly related to pancreatic cancer mortality, whereas IL-10 shows an inverse association." (PMID 38785507, 2024).
periapical abscess (1 paper, 2021). "The metabolic environment of periapical abscess may stimulate the conversion of LTB4 to a less active form, 20-HETE, and the downregulation of IL-12A." (PMID 34539639, 2021).
prediabetes (1 paper, 2019). "Interestingly, however, a direct association was observed between IL-33 and IL-12A in individuals with T2D but not in those with normoglycemia or prediabetes." (PMID 31073344, 2019). "Furthermore, IL-33 was directly correlated with IL-12A (IL-12B was not tested) in individuals with T2D (r = 0.42; P = 0.007; n = 41) but not in those with normoglycemia or prediabetes." (PMID 31073344, 2019).
radicular cyst (1 paper, 2021). "In our study, IL-12A was the most upregulated gene in radicular cyst compared with other periapical lesions." (PMID 34539639, 2021). "IL-12A gene expression was significantly increased in the radicular cyst rather than healthy pulp tissue (P < 0.01)." (PMID 34539639, 2021). "Immunological markers such as IL-12A may play a critical role in the maintenance of memory CD8 T cells, in radicular cysts." (PMID 34539639, 2021).
rectal cancer (1 paper, 2024). A primary or metastatic malignant neoplasm that affects the rectum. "CXCL10, IL12A, CD247 and ITGB1 were identified as predictive markers for the response to neoadjuvant treatment in rectal cancer in previous studies." (PMID 38406803, 2024).
Senile plaques (1 paper, 2022). Senile plaques are extracellular deposits of amyloid in the gray matter of the brain. "One with high expression levels of IL-1β, TNF-α and IL-12A typical of a pro-inflammatory phenotype related with oligomeric Aβ, the other located near senile plaques with upregulation of IL-1ra, Arginase 1 and FIZZ, is characteristic of a reparative phenotype." (PMID 35011699, 2022).
systemic sclerosis (1 paper, 2018). A chronic disorder, possibly autoimmune, marked by excessive production of collagen which results in hardening and thickening of body tissues. "SCHIP1 has been reported along with IL12A as a potential systemic sclerosis gene which functions in immune regulation via T cell activity." (PMID 30373671, 2018).
thymoma (1 paper, 2021). A neoplasm arising from the epithelial cells of the thymus. "The findings about different expression of inflammatory gene such as IL12A and IL31RA in thymoma with or without MG further confirmed the evidence that the incidence of MG may associated to infection." (PMID 34777476, 2021).
toxoplasmosis (1 paper, 2019). A parasitic disease contracted by the ingestion or fetal transmission of toxoplasma gondii. "In the KEGG results, we found that DF‐related genes, STAT1 and IL12A, were enriched in the signaling pathway of ‘toxoplasmosis’, and MAGED1 was enriched in ‘protein processing in endoplasmic reticulum’." (PMID 30868055, 2019).
undifferentiated thyroid carcinoma (1 paper, 2024). "Regarding the role of IL-12A p35, its expression levels are weakly expressed in undifferentiated thyroid carcinoma (ATC group) (densitometric analysis A1)." (PMID 39200219, 2024).
upper respiratory tract infection (1 paper, 2012). "IL-12A mRNA expression was increased when SHS was administered from one day before to 4 days p.i. on upper respiratory tract infection." (PMID 23346216, 2012).
uveitis (1 paper, 2022). An inflammatory process affecting a part of or the entire uvea. "Furthermore, the p35-KI mouse, which is hemizygous at the il12a locus, develops more severe uveitis because of reduced IL-35 expression." (PMID 35897732, 2022).
tumor (61 papers, 2011 to 2026). "The cytokine IL10, which showed high expression in the high m5CrLS score, could inhibit the release of IL12A from dendritic cells, thus causing anti-tumor immunosuppressive effects." (PMID 35309316, 2022). "The expressions of both EBI3 and IL12A are associated with larger tumor size and Ki‐67 expression." (PMID 33064893, 2020). "Whereas others reported the production of immunosuppressive cytokines in different conditions and B cell subpopulations, we did not detect an upregulation of genes associated with immunosuppression in tumor-derived B cells, namely Il-12a, Ebi3 (which together form IL-35) and Il-10." (PMID 30972056, 2019). "We found that IL-12A expression was higher in tumor tissues of mice receiving PD-1/PD-L1 antibodies than in baseline data and that the tight junction and NSCLC pathway were also activated in non-responders." (PMID 40259042, 2025). "Subsequent investigations revealed that IL-12A overexpression stimulated the expression of angiogenesis-associated proteins TIMP1, IGFBP1, and PAI1 in tumor cells." (PMID 39974277, 2025). "By processing multiple scRNA-seq datasets across three murine GB cell lines (CT-2A, GL261, and 005) with different genetic and phenotypic profiles and analyzing GB tumor cells, we confirmed a trend of low Il12a/b gene expression in the TME and the tumor cells." (PMID 40842154, 2025). "IL-12a then further activates natural killer cells and T cells, enhancing the body’s anti-tumor immune capacity." (PMID 40462156, 2025). "The qRT-PCR analysis of tumor tissues revealed that Flagrp170-gp100 immunization significantly elevated Th1 immunity-related cytokine genes, including ifng and il12a." (PMID 41295469, 2025). "Next, possibilities of NFκB-based transcriptional regulation of Il10 and Il12a genes due to NLGP-Dectin-1 transduced signal were explored within nuclei of tumor-conditioned mBMDCs, following nuclear translocations of the NFκB subunits, p65 and p50." (PMID 38649988, 2024). "Quantitative PCR (qPCR) of whole tumor lysate for transcript levels of the cytokines TGFβ (Tgfb1–2), IL10 (Il10), and IL35 (Ebi3 and Il12a), associated with suppressed antitumor immunity, showed reduced levels in Vegfr2Y1173F/+ tumors." (PMID 37651195, 2023). "Firstly, it can promote IL-12a production in DCs by enhancing H3K27ac binding at the IL-12a enhancer regions, to promote anti-tumor immunity of CD8+ T cells." (PMID 38169949, 2023). "IL12A is a potent immunosuppressive cytokine produced by regulatory B cells, Treg cells, macrophages, dendritic cells, and tumor cells, which suppresses the effector functions of CD4+ and CD8+ T cells but strongly favors Treg proliferation." (PMID 34745101, 2021). "By averaging z‐score expression levels per tumor, tumors with DDR mutation had lower expression levels of CTLA‐4, IFNG, TNF, FAS, and VTCN1, and higher expression levels of IL6, IL1B, and IL12A compared with the DDR wild‐type ones." (PMID 31991061, 2020). "In the present study, we separately evaluated the tumor expression level of the IL-12 encoding genes IL12B and IL12A." (PMID 31004093, 2019). "In the 4T1-BALB/c syngeneic tumor model, an upregulation of Ebi3 and Il12a was confirmed in mTAMs compared with pTAMs." (PMID 30218063, 2018). "TAMs from SNAIL1 depleted tumors displayed increased expression of M1-like/anti-tumor genes like Ifna1, Il12a, Il6, Nos2, and Ifnb1." (PMID 29593211, 2018). "These evaluations also showed that the presence of tumours in WT mice provoked a slight but significant decrease in Cd3g, Il6 and Il12a expression in this immune organ." (PMID 30166561, 2018). "qRT-PCR assays revealed an increase in Il12a levels specifically in tumor-infiltrating macrophages from myeloid cell-KO mice." (PMID 29180626, 2017). "The inflammatory markers IL6 and IL8 as well as the potential HPV receptor ITGA6 were significantly elevated while IL12A was downregulated in the tumour tissues." (PMID 23570247, 2013).